PGR (progesterone receptor)
Diseases named in the same sentence as PGR in open-access papers (continued):
Sharing a sentence is not in itself a finding about the gene and the disease.
lupus (1 paper, 2025). "Progesterone receptor (PR) deficiency in lupus-prone mice leads to reduced Treg and increased Tfh cells." (PMID 40806232, 2025).
Lynch syndrome (1 paper, 2021). An autosomal dominant hereditary neoplastic syndrome characterized by the development of colorectal carcinoma and a high risk of developing endometrial carcinoma, gastric carcinoma, ovarian carcinoma, renal pelvis carcinoma, and small intestinal carcinoma. "There was no consensus whether progesterone receptor status should be considered and if patients with Lynch syndrome could be considered as appropriate candidates." (PMID 33546293, 2021).
male infertility (1 paper, 2015). The inability of the male to effect fertilization of an ovum after a specified period of unprotected intercourse. "Our results indicated that polymorphisms of the +331G/A and progins of the PGR gene are unrelated to male infertility, at least in a Chinese population." (PMID 25653674, 2015). "The aim of the present study was to investigate whether there is any relationship between male infertility and two known PGR gene polymorphisms: progins and +331G/A." (PMID 25653674, 2015). "It therefore seemed plausible that polymorphisms in the human PGR gene might also affect male fertility; in particular, it has been suggested that some cases of male infertility may be due to deficiencies in the expression of the PGR and the resulting insensitivity to progesterone." (PMID 25653674, 2015). "To date, there have been no reports on the potential links between male infertility and polymorphisms of PGR gene." (PMID 25653674, 2015).
male pattern baldness (1 paper, 2021). "However, progesterone receptor expression does not significantly increase or decrease in in mesenchymal cells in male pattern baldness." (PMID 33803764, 2021).
menopause (1 paper, 2023). Cessation of menstruation, occurring in (e.g.) the human female usually around the age of 50. "PS extract has been reported to relieve menopause symptoms, without endometrial hyperplasia or cancer, through the regulation of the ERβ/ERα ratio, by increasing only ERβ without regulating ERα through the progesterone receptor." (PMID 37299404, 2023).
mesenchymal tumor (1 paper, 2023). "Fluid analysis results were positive for estrogen and progesterone receptor-positive mesenchymal tumor." (PMID 37261137, 2023).
mesonephric neoplasm (1 paper, 2025). An epithelial neoplasm of the female reproductive system arising from mesonephric remnants. "Most tumors were positive for cytokeratin-7 (8/9), EMA (9/9), estrogen and progesterone receptor (9/9), CD10 (7/9, including a luminal pattern reminiscent of mesonephric neoplasms), nuclear β-catenin (8/9), and CDX2 (8/9)." (PMID 38418687, 2025).
metastatic prostate carcinoma (1 paper, 2016). A carcinoma that arises from the prostate gland and has spread to other anatomic sites. "Among these elements are two TFs (PGR and HOXD10) in the primary and three TFs (STAT3, JUN and JUNB) in the metastatic prostate cancer network." (PMID 28005952, 2016).
mucinous tumor (1 paper, 2011). "All the lobular (5/113) and mucinous tumors (5/113) were ER+/PgR+/Her-2/neu− (luminal type) and all were negative for the basal CKs, except one mucinous tumor that was found to be positive for CK5/6." (PMID 21274453, 2011).
muscular atrophy (1 paper, 2023). The loss of muscle tissue due to inactivity or disease. "However, the major drawback of DEX usage causes depression via the modulation of cellular glucose metabolism and AMPK/mTOR signaling pathways; alterations in the vascularization process via the modification of progesterone receptor actions; and enhances muscular atrophy." (PMID 37242430, 2023).
myocardial ischemia (1 paper, 2021). A disorder of cardiac function caused by insufficient blood flow to the muscle tissue of the heart. "Taken together, these observations indicate that AR and PGR are potential druggable targets for myocardial ischemia, while their pharmacological targeting can be complicated due to drug compounds’ activities towards other sex hormone receptors." (PMID 34404849, 2021).
neuroblastoma (1 paper, 2022). Neuroblastoma (NB) is the most common solid, extracranial childhood tumor. "Interestingly, both ETO and PG administration in neuroblastoma cell lines, expressing both PHOX2B and nuclear PGR, induced a direct reduction in PHOX2B expression, as well as reduced promoter activity of PHOX2B target genes." (PMID 35563209, 2022).
ocular infection (1 paper, 2025). "Hence, the progesterone receptor or androgen receptor may play a role in the sex-dependent HSV-1 effects that were observed during acute ocular infection and/or explant-induced reactivation in KLF15−/− mice." (PMID 40872334, 2025).
oligospermia (1 paper, 2015). Decreased number of spermatozoa in the semen. "In addition, while the 306 bp insertion/deletion progins polymorphism was detected in the PGR gene of the test subjects, only two individuals with oligospermia had the I/D hybrid genotype There were no I/I homozygous individuals among the test subjects." (PMID 25653674, 2015).
oral cavity cancer (1 paper, 2022). A primary or metastatic malignant neoplasm involving the oral cavity. "Several studies have found ER and PgR in oral cavity cancer." (PMID 36233715, 2022). "In oral cavity cancer, EGRF has been reported to be involved in the mitogen-activated protein (MAPK) and focal adhesion kinase (FAK) pathways via the ER Although ER and PgR expression has been demonstrated in oral cavity cancer, the role of sex hormones in tumor development remains uncertain." (PMID 36233715, 2022).
ovarian mucinous cancers (1 paper, 2025). "Similarly, IHC markers progesterone receptor and vimentin have been reported to improve classification accuracy of ovarian mucinous cancers but were not evaluated in this study." (PMID 40981433, 2025).
Pancreatic cysts (1 paper, 2018). A cyst of the pancreas that possess a lining of mucous epithelium. "The role of progesterone receptor (PR) has been reported in a series of pancreatic cysts." (PMID 30547767, 2018).
papillary adenocarcinoma (1 paper, 2008). A morphologic variant of adenocarcinoma. "A representative of these genes, which could potentially serve as a target for therapeutic intervention, is the progesterone receptor (PR) which was expressed at over fourfold higher levels in the papillary adenocarcinoma compared to the carcinoma." (PMID 18811984, 2008).
Papillary breast carcinomas (1 paper, 2024). "Papillary breast carcinomas are characterized by estrogen receptor (ER), progesterone receptor (PR), and/or human epidermal growth factor receptor 2 (HER2) positivity, allowing for targeted therapeutic approaches with favorable outcomes." (PMID 39385920, 2024).
PEComas (1 paper, 2007). "Estrogen receptor (ER) and progesterone receptor (PR) expression, that have been reported primarily in the spindle cell component of PEComas, may play a role in the development of this morphologic pattern." (PMID 18053181, 2007).
peritoneal carcinoma (1 paper, 2016). A peritoneum cancer that is located in the inside of the abdomen.
peritoneal disease (1 paper, 2014). "The first patient had low-grade ULMS strongly ER and PgR positive with low volume peritoneal disease." (PMID 25018868, 2014).
pituitary adenomas (1 paper, 2022). "Another lncRNA, called C5orf66-AS1, regulates several genes, including PAQR7, a progesterone receptor that causes a progesterone A-B receptor-independent reduction in GnRH, whose expression has been found to have a role in progression and invasion of null-cell pituitary adenomas." (PMID 35432200, 2022).
polyp (1 paper, 2024). A usually exophytic mass attached to the underlying tissue by a broad base or a thin stalk. "Regarding gene expression characteristics in polyp tissues, some studies showed that postmenopausal bleeding EP patients exhibited higher estrogen receptor, progesterone receptor, KI67, and BCL2 levels in the polyp epithelium and stroma compared to the adjacent endometrium." (PMID 38473810, 2024).
prostate (1 paper, 2015). "Previous publications on PGR expression in PCa, especially those using IHC, have presented contradicting results and only a few reports have addressed PGR’s role in prostate carcinogenesis." (PMID 25723513, 2015).
prostate tumors (1 paper, 2016). "Survival curves based on the key molecules (HOXD10 and PGR) in primary prostate tumors shows significance differences between the high expression and low expression groups (P-value < 0.05)." (PMID 28005952, 2016). "Based on the regulatory network analysis of primary prostate tumor, HOXD10, BCL2 and PGR are 3 key elements in the network." (PMID 28005952, 2016).
pulmonary neoplasms (1 paper, 2016). "Su and colleagues showed a positive PgR expression with negative ER status in 33% of pulmonary neoplasms collections, with 2% of positivity for both ER and PgR." (PMID 27690341, 2016).
retinal degeneration (1 paper, 2022). Degeneration of the retina. "The classical progesterone receptor, PGR, was not identified in the proteome dataset but has been previously identified in the retina of rd10 mice (rd10, retinal degeneration 10), a model for retinitis pigmentosa, and C57 wild type mice." (PMID 36266625, 2022).
salivary glands tumors (1 paper, 2018). "In salivary gland tumors (SGTs), little and conflicting information about the role of the estrogen receptor alpha (ERα), progesterone receptor (PgR) and androgen receptor (AR) has been described and in most cases the use of sex hormone antagonists is not contemplated in clinical practice." (PMID 29385707, 2018). "More recent studies described ER and PgR positivity in only a few cases while, as in our case, a large case series (139 salivary glands tumors) study never detected ERα and PgR positivity." (PMID 29385707, 2018).
schwannoma (1 paper, 2009). A benign, usually encapsulated slow growing tumor composed of Schwann cells. "Thirty-three percent of the schwannomas (7/21) showed a strong band for progesterone receptor mRNA by PCR-Southern blot analysis; there were an equal number of males and females in this group." (PMID 19889208, 2009).
skin cutaneous melanoma (1 paper, 2022). "HER3 was highly expressed in skin cutaneous melanoma, prostate adenocarcinoma, intestinal-stomach adenocarcinoma and estrogen receptor-positive (ER+), progesterone receptor-positive (PR+), HER2− breast cancer (ER+/PR+/HER2−), while generally lower in normal tissues." (PMID 36137139, 2022).
spinal meningioma (1 paper, 2022). Spinal meningioma isa rare type of spinal cord cancer. "Only a few studies have exclusively investigated this interesting pathophysiological pathway for spinal meningiomas but could not find a significant correlation of progesterone receptor expression with the MIB-1 index." (PMID 35205781, 2022).
squamous cell lung carcinoma (1 paper, 2021). A carcinoma arising from squamous bronchial epithelial cells. "In a very recent study, findings show that ZNF540 and PGR were among top 267 down-regulated genes in the squamous cell lung cancer tissues compared to the adjacent normal tissues." (PMID 34061869, 2021).
thyroid autoimmunity (1 paper, 2024). "The modulation of ISGs, PGR, and PIBF is related to thyroid autoimmunity, the synthesis and release of T4 and T3." (PMID 38665088, 2024). "Early pregnancy affects expression of ISGs, PGR, and PIBF in maternal thyroid through IFNT and progesterone, which may regulate thyroid autoimmunity and thyroid hormone secretion in ewes." (PMID 38665088, 2024).
thyroid disorders (1 paper, 2022). "The overall prevalence of thyroid disorders, mainly nontoxic goiter and HT, is increased in patients with ductal BC (almost 28% and 14%, respectively), such prevalence being independent from both the estrogen receptor (ER) and progesterone receptor (PR) status of the BC." (PMID 35683541, 2022).
vascular malformation (1 paper, 2023). A non-neoplastic disorder that is the result of defects of vascular morphogenesis. "In these studies, expression of GHR, FSHR, and PGR was reported mostly in endothelium of vascular malformations." (PMID 37864259, 2023). "Several studies have demonstrated that specific hormone receptors (HR) such as progesterone receptor (PGR), growth hormone receptor (GHR), and follicle-stimulating hormone receptor (FSHR) were present in vascular tumors and vascular malformations." (PMID 37864259, 2023).
Vestibular schwannoma (1 paper, 2009). A vestibular schwannoma (also known as acoustic neuroma, acoustic neurinoma, or acoustic neurilemoma) is a benign, usually slow-growing tumor that develops from the VIIIth cranial nerve supplying the inner ear. "The objective was to determine the expression of estrogen and progesterone receptors in vestibular schwannomas as well as to determine predictive factors for estrogen and progesterone receptor positivity." (PMID 19889208, 2009). "No estrogen and progesterone receptor could be found in any of our 100 cases of vestibular schwannoma." (PMID 19889208, 2009). "No estrogen and progesterone receptor could be found in any of our 100 cases of vestibular schwannomas." (PMID 19889208, 2009).
tumor (2,139 papers, 1980 to 2026). "In multivariable analysis, baseline tumor T stage, progesterone receptor expression, and AR expression were independently associated with DFS." (PMID 42200015, 2026). "Additional factors associated with poorer outcomes included liver metastasis, progesterone receptor negativity, high tumor grade, and the concurrent use of fulvestrant with CDK4/6 inhibitors." (PMID 39859134, 2025). "For AI-based imaging examinations, quantitative imaging features related to tumor-associated biomarkers, such as estrogen receptor (ER) and progesterone receptor (PR), play a critical role in the early screening of endometrial cancer." (PMID 40249940, 2025). "Conversely, HER2 overexpression is the hallmark of ERBB2-overexpressing tumours, which also lack ER and progesterone receptor (PR) expression." (PMID 40824193, 2025). "Special attention was given to early changes in Ki-67 and PgR expression and their association with treatment outcomes, including tumor downstaging, response classification, and surgical conversion rates." (PMID 40723203, 2025). "After adjusting for baseline PgR status, tumor size, and age at diagnosis, the association between baseline proliferation and RFI remained non-significant IHC-Ki67 (HR = 1.76, 95 %CI: 0.23–13.50) and SSP-Ki67(HR = 0.65, 95 %CI: 0.21–2.03)." (PMID 41242143, 2025). "Several studies have established a correlation between tumor-associated neutrophils and favorable prognostic parameters, such as the overexpression of PgR, a low proliferative index, and a low histological grade, as well as longer survival." (PMID 40136347, 2025). "Another tumor in T12-L1 showed diffuse immunopositivity for progesterone receptor and epithelial membrane antigen; the Ki-67 labeling index was about 5%, and smooth muscle-associated tumor was excluded by markers of smooth muscle actin and desmin." (PMID 39792750, 2025). "Tumours positive for both ER and PgR were also associated with positive Cathepsin D expression (p = 0.037)." (PMID 38578521, 2024). "In BCLM, most tumor conversions are the result of loss of ER/PgR expression or amplification of Her2." (PMID 37705026, 2023). "Tumor-associated macrophages have been widely associated with poor prognosis, angiogenesis, and loss of PgR in EC." (PMID 37730563, 2023). "High ezrin expression was significantly associated with adverse survival of patients whose tumours were categorised as receptor (ER, PgR or HER2) positive (p < 0.001) in comparison to those categorised as triple‐negative breast cancer (p = 0.889)." (PMID 36938826, 2023). "Estrogen receptor 1 (ESR1) and a progesterone receptor (PGR) were reported to participate in lipid metabolism by encoding estrogen or steroid receptors to promote tumor progression." (PMID 36900015, 2023). "There are minimal research on tumor estrogen receptor (ER) and progesterone receptor (PR) status, as well as breast cancer risk in systemic and organ-specific autoimmune disorders." (PMID 37007960, 2023). "Performance of the 21-gene testing was associated with older age, lower tumor grade, T1 stage, lower number of positive lymph nodes, and progesterone receptor-positive disease (all P < 0.05)." (PMID 36875478, 2023). "ARID1A-mutated EC exhibit decreased PgR transcription levels, which are associated with changes in the PgR enhancer region during early tumor development." (PMID 37730563, 2023).